OR7M1P (olfactory receptor family 7 subfamily M member 1 pseudogene)
Gene: Unprocessed pseudogene on chromosome 10 (133,481,238 to 133,481,770, forward strand). Ensembl gene ENSG00000273336.
Diseases named in the same sentence as OR7M1P in open-access papers:
OR7M1P is named in the same sentence as 1 disease in open-access papers, as found by Europe PMC text mining. Sharing a sentence is not in itself a finding about the gene and the disease.
OR7M1P shares sentences with these, for which no sentence is quoted: autism (1 paper).